ACHE (acetylcholinesterase (Yt blood group))
Description:
Hydrolyzes rapidly the acetylcholine neurotransmitter released into the synaptic cleft allowing to terminate the signal transduction at the neuromuscular junction. Role in neuronal apoptosis.
Synonyms: ACEE; ARACHE; N-ACHE; YT
Tractability: Small molecule: an approved drug acts on it; a structure with a bound ligand is known; a high-quality ligand is known; it has a high-quality binding pocket; it belongs to a druggable protein family. Antibody: its Gene Ontology location is reachable by antibodies, with high confidence; UniProt places it where antibodies can reach, with medium confidence; UniProt predicts a signal peptide or a membrane-spanning region. PROTAC: a small molecule that binds it is known.
Target class: Enzyme; Hydrolase
Chemical probes: CHEMBL3215768, HUPRINE Y, NEOSTIGMINE, PD080795, PD081611, PD082243, PD084143, PD134456, PD134457, PD134458, PD134459
Safety:
Unwanted effects reported when the protein is acted on. In parentheses: how it was acted on, where the effect was seen, and who reports it.
bronchoconstriction (Lynch et al. (2017): inhibition, acute dosing, nervous system, respiratory, cardiovascular, gastrointestinal; Bowes et al. (2012): inhibition, cardiovascular system, pulmonary, gastrointestinal)
apnea (inhibition, acute dosing; nervous system, respiratory, cardiovascular, gastrointestinal; source: Lynch et al. (2017))
ataxia (inhibition, acute dosing; nervous system, respiratory, cardiovascular, gastrointestinal; source: Lynch et al. (2017))
autonomic dysfunction (inhibition, chronic dosing; nervous system, respiratory, cardiovascular, gastrointestinal; source: Lynch et al. (2017))
blurred vision (inhibition, acute dosing; nervous system, respiratory, cardiovascular, gastrointestinal; source: Lynch et al. (2017))
cognitive deficit (inhibition, chronic dosing; nervous system, respiratory, cardiovascular, gastrointestinal; source: Lynch et al. (2017))
coma (inhibition, acute dosing; nervous system, respiratory, cardiovascular, gastrointestinal; source: Lynch et al. (2017))
convulsions (inhibition, acute dosing; nervous system, respiratory, cardiovascular, gastrointestinal; source: Lynch et al. (2017))
death (inhibition, acute dosing; nervous system, respiratory, cardiovascular, gastrointestinal; source: Lynch et al. (2017))
Decrease, Population growth rate (inhibition; nervous system; source: AOP-Wiki)
decreased blood pressure (inhibition; cardiovascular system, pulmonary, gastrointestinal; source: Bowes et al. (2012))
decreased gastrointestinal motility (inhibition, acute dosing; cardiovascular system, pulmonary, gastrointestinal; source: Bowes et al. (2012))
decreased heart rate (inhibition; cardiovascular system, pulmonary, gastrointestinal; source: Bowes et al. (2012))
decreased pupil diameter (inhibition, acute dosing; nervous system, respiratory, cardiovascular, gastrointestinal; source: Lynch et al. (2017))
diarrhea (inhibition, acute dosing; nervous system, respiratory, cardiovascular, gastrointestinal; source: Lynch et al. (2017))
foot drop (inhibition, chronic dosing; nervous system, respiratory, cardiovascular, gastrointestinal; source: Lynch et al. (2017))
increased bronchial secretions (inhibition, acute dosing; nervous system, respiratory, cardiovascular, gastrointestinal; source: Lynch et al. (2017))
increased defecation (inhibition, acute dosing; nervous system, respiratory, cardiovascular, gastrointestinal; source: Lynch et al. (2017))
increased gastrointestinal motility (inhibition; cardiovascular system, pulmonary, gastrointestinal; source: Bowes et al. (2012))
Increased Mortality (inhibition; nervous system; source: AOP-Wiki)
increased respiratory secretions (inhibition; cardiovascular system, pulmonary, gastrointestinal; source: Bowes et al. (2012))
increased salivation (inhibition, acute dosing; nervous system, respiratory, cardiovascular, gastrointestinal; source: Lynch et al. (2017))
increased then decreased blood pressure (inhibition, acute dosing; nervous system, respiratory, cardiovascular, gastrointestinal; source: Lynch et al. (2017))
increased then decreased heart rate (inhibition, acute dosing; nervous system, respiratory, cardiovascular, gastrointestinal; source: Lynch et al. (2017))
increased urine excretion (inhibition, acute dosing; nervous system, respiratory, cardiovascular, gastrointestinal; source: Lynch et al. (2017))
lacrimation (inhibition, acute dosing; nervous system, respiratory, cardiovascular, gastrointestinal; source: Lynch et al. (2017))
mood change (inhibition, chronic dosing; nervous system, respiratory, cardiovascular, gastrointestinal; source: Lynch et al. (2017))
muscle relaxation (inhibition, acute dosing; nervous system, respiratory, cardiovascular, gastrointestinal; source: Lynch et al. (2017))
peripheral neuropathy (inhibition, chronic dosing; nervous system, respiratory, cardiovascular, gastrointestinal; source: Lynch et al. (2017))
tingling/weakness in limbs (inhibition, chronic dosing; nervous system, respiratory, cardiovascular, gastrointestinal; source: Lynch et al. (2017))
and 1 more effect
Gene: Protein-coding gene on chromosome 7 (100,889,994 to 100,897,022, reverse strand). Ensembl gene ENSG00000087085.
Subcellular location: Synapse; Secreted; Cell membrane; Nucleus (Isoform T); Cell membrane (Isoform H)
Subcellular location (Human Protein Atlas): Golgi apparatus; Vesicles
Pathways (Reactome):
Metabolism: Synthesis of PC
Metabolism of proteins: Synthesis, secretion, and deacylation of Ghrelin
Neuronal System: Neurotransmitter clearance
Gene Ontology:
Molecular function: acetylcholine binding; acetylcholinesterase activity; cholinesterase activity; collagen binding; hydrolase activity; laminin binding; protein binding; protein homodimerization activity; serine hydrolase activity; amyloid-beta binding; identical protein binding
Biological process: acetylcholine catabolic process; cell adhesion; osteoblast development; acetylcholine catabolic process in synaptic cleft; amyloid precursor protein metabolic process; negative regulation of synaptic transmission, cholinergic; nervous system development; positive regulation of cold-induced thermogenesis; positive regulation of protein secretion; synapse assembly
Cellular component: extracellular region; Golgi apparatus; membrane; neuromuscular junction; perinuclear region of cytoplasm; synapse; basement membrane; plasma membrane; cell surface; nucleus; synaptic cleft
Genetic constraint (gnomAD): Loss-of-function variants: 19 observed, 51.06 expected, observed/expected ratio (o/e) 0.37, 90% interval 0.26 to 0.55. The upper end of that interval is the gene's LOEUF score, 0.55, which puts it in group 2 of 6, group 1 being the genes least tolerant of losing a copy. Missense variants: 605 observed, 820.96 expected, observed/expected ratio (o/e) 0.74, 90% interval 0.69 to 0.79. Synonymous variants: 392 observed, 366.4 expected, observed/expected ratio (o/e) 1.07, 90% interval 0.98 to 1.16.
Homologues: Orthologues: macaque ACHE (99% identical), chimpanzee ACHE (94% identical), dog ACHE (93% identical), guinea pig ACHE (92% identical), rat Ache (89% identical), mouse Ache (88% identical), pig ACHE (87% identical), zebrafish ache (61% identical), tropical clawed frog ache (60% identical), Caenorhabditis elegans ace-3 (30% identical), Caenorhabditis elegans ace-4 (30% identical), Drosophila melanogaster CG4757 (28% identical), and 39 more. Paralogues in human: BCHE (50% identical), CES4A (31% identical), CES2 (31% identical), NLGN2 (30% identical), NLGN3 (30% identical), NLGN4X (30% identical), NLGN1 (29% identical), NLGN4Y (29% identical), CES3 (29% identical), CES1 (29% identical), CEL (29% identical), CES5A (29% identical), and 1 more.
Diseases named in the same sentence as ACHE in open-access papers:
ACHE is named in the same sentence as 302 diseases in open-access papers, as found by Europe PMC text mining. Sharing a sentence is not in itself a finding about the gene and the disease. The quoted sentences say what the papers report.
Alzheimer disease (898 papers, 2006 to 2026). A progressive, neurodegenerative disease characterized by loss of function and death of nerve cells in several areas of the brain leading to loss of cognitive function such as memory and language. "Cholinergic neuron impairment is a significant cause of cognitive decline in Alzheimer’s disease (AD), making acetylcholinesterase (AChE) a key therapeutic target." (PMID 40733311, 2025). "This role becomes particularly significant in Alzheimer disease (AD), where AChE levels decline due to neuronal loss." (PMID 40612057, 2025). "The dysfunction of AChE is associated with various neurological diseases, particularly Alzheimer’s disease, where its reduced activity leads to cognitive decline." (PMID 39860266, 2025). "ex G.Don) Steenis, as a source of bioactive compounds for the inhibition of AChE and BuChE, two enzymes implicated in Alzheimer’s disease AD." (PMID 40911700, 2025). "On the other hand, chlorogenic acid, a phenolic acid derived from a natural source, has been shown to have neuroprotective properties and an AChE inhibitory effect associated with Alzheimer’s disease." (PMID 40298661, 2025). "Alzheimer’s disease (AD) is a neurodegenerative disorder categorized by the progressive loss of cognitive function, with acetylcholinesterase (AChE) and butyrylcholinesterase (BuChE) as key therapeutic targets." (PMID 40911700, 2025). "Alzheimer’s disease (AD) is the most common cause of dementia, and the inhibition of acetylcholinesterase (AChE) is a key approach in treating AD." (PMID 39860136, 2025). "The inhibition of acetylcholinesterase (AChE) is a cornerstone strategy for treating types of dementia such as Alzheimer’s disease (AD), where there is a progressive loss of acetylcholine (ACh) in the brain." (PMID 40362522, 2025). "The abnormal levels of the human carbonic anhydrase isoenzymesI and II (hCA I and II) and cholinesterase enzymes, namely, acetylcholinesterase(AChE) and butyrylcholinesterase (BChE), are linked with various disordersincluding Alzheimer’s disease." (PMID 38737075, 2024). "Unfortunately, the brains of individuals with Alzheimer’s disease have lower levels of acetylcholine compared to healthy individuals, which is associated with increased AChE activity." (PMID 39458923, 2024). "This plant extract's inhibition of AChE and BChE enzymes indicates its potential to preserve brain function and mitigate the risk of Alzheimer's disease." (PMID 39698089, 2024). "For example, ACHE is a target of drugs for Alzheimer’s disease, including Donepezil and Galantamine, which cause bradycardia as a side effect." (PMID 38969939, 2024). "Current therapies for cognitive loss caused by Alzheimer’s disease include acetylcholinesterase (AChE) inhibitors and muscarinic or nicotinic receptor ligands." (PMID 39092234, 2024). "The cholinergic dysfunction, marked by exacerbated cholinesterase activities (AChE and BChE), is well recognized in Alzheimer's disease (AD), the most prevalent cause of dementia." (PMID 38539199, 2024). "An imbalance of AChE enzyme concentration is linked to several neurological disorders, including Alzheimer’s disease, dementia, Parkinson’s disease, and schizophrenia, making AChE and ACh significant physiological biomolecules." (PMID 36832043, 2023). "Cinnamon leaf oil was evaluated using several in vitro bioanalytical assays for its antioxidant properties and inhibitory effects on metabolic enzymes, such as AChE, α-amylase, and CA II, which are associated with diabetes, Alzheimer’s disease, and glaucoma." (PMID 36676085, 2023). "Acetylcholine is considered one of the best-studied neurotransmitters and has been linked to Alzheimer’s disease pathogenesis (neurodegenerative disease and the leading cause for dementia), and its hydrolysis is catalyzed by AChE." (PMID 36985342, 2023).
Alzheimer disease (continued). "The inhibition of key enzymes linked to Alzheimer’s disease (AD), such as acetylcholinesterase (AChE) and butyrylcholinesterase (BChE), is an important task for identifying novel and safe medicine from natural sources, especially those found in native plants." (PMID 36840166, 2023). "AChE has been extensively studied in the tissues involved in Alzheimer’s disease (AD) since the finding of the cholinergic deficiency." (PMID 35328542, 2022). "The presence of acetylcholinesterase (AChE) is linked to a plaque of extracellular β-amyloid protein (Aβ) deposits and neurofibrillary tangles in Alzheimer's disease, the most common NDD." (PMID 35310033, 2022). "Abnormal levels of AChE are associated widely with neurodegenerative disorders such as myasthenia gravis, Parkinson’s disease (PD), and Alzheimer’s disease (AD)." (PMID 36364255, 2022). "Pharmacological inhibition of cholinesterase (ChE) enzymes (acetylcholinesterase (AChE) and/or butyrylcholinesterase) is the most common treatment for Alzheimer’s disease (AD) and its associated complications." (PMID 35372507, 2022). "Acetylcholinesterase (AChE) is an enzyme implicated significantly in neurodegenerative diseases, particularly Alzheimer’s disease (AD)." (PMID 36431011, 2022). "Increased AChE activity cause the loss of cholinergic neurotransmissions leading to Dementia and Alzheimer’s disease." (PMID 33669503, 2021). "AChE inhibitors reduce AChE activity and maintain or increase ACh levels, which are typically deficient in Alzheimer’s disease (AD), and thus, enhance cholinergic transmission in brain." (PMID 32859055, 2020). "The inhibition of the enzyme acetylcholinesterase (AChE) is one of the pathways to countering the cholinergic deficit associated with cognitive dysfunction diseases like in Alzheimer’s disease." (PMID 32354114, 2020). "Peripheral anionic binding site of the enzyme is also associated with the AChE-mediated abnormal β-amyloid protein aggregation in Alzheimer’s disease patients." (PMID 32991579, 2020). "The imbalance in AChE activity can cause various types of neurodegenerative pathologies such as Alzheimer’s disease (AD) and Parkinson’s disease (PD)." (PMID 32401067, 2020). "ACHE encodes the target for acetylcholinesterase inhibitors such as donepezil and galantamine, which are licenced treatments for Alzheimer’s disease." (PMID 32954289, 2020). "Pathogenesis of Alzheimer’s disease correlates with deficiency of acetylcholinesterase (AChE) in the brain." (PMID 30925771, 2019). "In Alzheimer's disease, the increased activity of the AChE leads to the breakdown of the ACh that causes depletion of acetylcholine level, resulting into impaired cholinergic functions in the brain." (PMID 31114535, 2019). "Alzheimer's disease (AD) is one of the most common causes of dementia, and acetylcholinesterase inhibitors (AChE) are the most commonly used drugs to treat this disease." (PMID 30577562, 2018). "Although, inhibition of AChE is still considered as the main therapeutic strategy to treat Alzheimer’s disease, other events are implicated in the physiopathology of this disease." (PMID 30551576, 2018). "The linear and cyclic AChE-peptides show antagonistic site-selective actions in regulating availability of key neurochemicals linked to Alzheimer's disease." (PMID 29950969, 2018). "Mainly, loss of AChE is evident in forebrain of Alzheimer’s disease (AD) patients, which are revealed from Positron emission tomography and autopsy studies." (PMID 29263397, 2017). "The entorhinal cortex is one of the first areas affected in Alzheimer’s disease and both AChE and zinc have been implicated in its onset and progression." (PMID 28443003, 2017). "Recently, a study has revealed that acetylcholinesterase (AChE), which is one of the risk factors of Alzheimer’s disease (AD), is increased by TMT." (PMID 28817076, 2017).
Alzheimer disease (continued). "AChE is an important target for treatment of various cholinergic deficiencies, including Alzheimer’s disease and myasthenia gravis." (PMID 28867801, 2017). "Meanwhile, BChE has been considered to be directly associated with the side effects of the AChE inhibitors and the existing drugs of Alzheimer's disease." (PMID 25506036, 2014). "In humans, AChE activity generally increases with age; furthermore, the elevated AChE activity has been linked to neurodegenerative diseases, e.g., Alzheimer's disease, Parkinson's disease, multiple sclerosis and Restless legs syndrome (RLS)." (PMID 24699280, 2014). "AChE has regained great attention recently due to its association with Alzheimer's disease (AD) and other neurodegenerative diseases characterized by low ACh levels owing to catabolism by AChE." (PMID 25558991, 2014). "An important therapeutic use of AChE inhibitors is in the treatment of dementia associated with Alzheimer’s disease." (PMID 24528673, 2014). "Inhibition of AChE is associated with treatment of several diseases such as Alzheimer’s disease (AD), myasthenia gravis, and glaucoma as well as the mechanisms of insecticide and anthelmintic drugs." (PMID 24381529, 2013). "Novel drugs for Alzheimer’s disease or antidotal therapy are tested by in vitro methods when AChE is implicated in the treatment process." (PMID 21731462, 2011). "The use of AChE inhibitors in order to enhance cholinergic function in the brain is the main strategy in treatment of Alzheimer’s disease (AD) which is characterized by loss or decline in memory and cognitive impairment." (PMID 21589805, 2009). "Our finding that CPF and DZN induce both AChE isoforms while CPO induces only the AChE-R variant is in agreement with findings from Alzheimer disease therapeutics." (PMID 17366821, 2007). "AChE is not only the primary target of neurotoxic agents and organophosphorus pesticides but its aberrant activity is also closely associated with various neurodegenerative diseases such as Alzheimer's disease (AD) and myasthenia gravis." (PMID 41836758, 2026). "However, AChE is also implicated in the pathology of Alzheimer’s disease (AD) due to its involvement in amyloid plaque formation." (PMID 40559280, 2025). "Alzheimer's disease (AD) is associated with AChE and BACE1 enzymes." (PMID 40041377, 2025). "The ability of MsEO to inhibit AChE suggests a promising potential for modulating acetylcholine levels, which could contribute to improving cognitive symptoms associated with Alzheimer’s disease." (PMID 39858504, 2025). "AChE inhibitors are designed to enhance acetylcholine levels in the brain, thereby improving cholinergic neurotransmission and alleviating cognitive deficits associated with Alzheimer’s disease." (PMID 40243991, 2025). "Research indicates that levels of the enzyme BuChE increase and may assume the role of metabolizing acetylcholine at synapses as the activity of AChE declines due to the gradual loss of cortical neurons in Alzheimer’s disease." (PMID 40553197, 2025). "In diseases such as Alzheimer’s disease, excessive activity of AChE can, in particular, cause communication disorders between nerve cells, which may aggravate the symptoms of the disease." (PMID 39771015, 2024). "Alzheimer’s disease (AD) is a neurodegenerative disorder associated with the dysregulation of several key enzymes, including acetylcholinesterase (AChE), cyclooxygenase-2 (COX-2), glycogen synthase kinase 3β (GSK-3β), β-site amyloid precursor protein cleaving enzyme 1 (BACE-1), and caspase-3." (PMID 39598743, 2024). "Alzheimer’s disease is one of the most common progressive neurodegenerative disorders related to a deficiency of acetylcholine and butyrylcholine, which are hydrolyzed by AChE and BChE, respectively." (PMID 39202972, 2024).